TNXA (tenascin XA (pseudogene))
Synonyms: XA; D6S103E; HXBL; formerly TNX
Gene: Transcribed unprocessed pseudogene on chromosome 6 (32,008,614 to 32,012,472, reverse strand). Ensembl gene ENSG00000248290.
Diseases named in the same sentence as TNXA in open-access papers:
TNXA is named in the same sentence as 15 diseases in open-access papers, as found by Europe PMC text mining. Sharing a sentence is not in itself a finding about the gene and the disease. The quoted sentences say what the papers report.
congenital adrenal hyperplasia (4 papers, 2021 to 2024). Congenital adrenal hyperplasia (CAH) is an inherited endocrine disorder caused by a steroidogenic enzyme deficiency that is characterized by adrenal insufficiency and variable degrees of hyper or hypo androgyny manifestations, depending of the type and the severity of the disease. "This latter deletion is similar to others in this highly variable and repetitive region that are known to cause the formation of the chimeric gene TNXA/TNXB, which may lead to congenital adrenal hyperplasia in combination with connective tissue dysplasia." (PMID 34946907, 2021). "NAHR-mediated deletion between TNXB and TNXA leads to loss of CYP21A2, the causal gene of autosomal recessive 21-hydroxylase deficiency (classical congenital adrenal hyperplasia, CAH), as well as C4B, absence of which may contribute to reduced complement 4 production." (PMID 39629471, 2024).
bladder cancer (2 papers, 2014 to 2022). "It is likely that deregulation of TNXA plays a key role in the development and/or progression of bladder cancer." (PMID 36324509, 2022). "Data analysis showed that KRT19P3 was upregulated and TNXA, CTA-134P22.2 and CTC-276P9.1 were downregulated in bladder cancer samples compared with matched normal tissues." (PMID 24944692, 2014). "For further validation of microarray results, qPCR was performed to evaluate the expression patterns of TNXA, CTA-134P22.2, CTC-276P9.1 and KRT19P3 in a total of 51 patients with bladder cancer." (PMID 24944692, 2014).
Ehlers-Danlos syndrome (2 papers, 2018 to 2023). The Ehlers–Danlos syndromes (EDS) are a clinically and genetically heterogeneous group of heritable connective tissue disorders (HCTDs) characterized by joint hypermobility, skin hyperextensibility, and tissue fragility. "To date, at least nine kinds of chimeric TNXA/TNXB genes have been identified and associated with Ehlers-Danlos syndrome as well as with CAH." (PMID 30559721, 2018).
type 1 diabetes (1 paper, 2012). "The only gene demonstrating evidence of association of accumulations of minor alleles with increased risk of type 1 diabetes was TNXA, with odds ratio 2.346 (1.772–3.107) per minor allele." (PMID 22951892, 2012). "The common SNP could not fully explain rare variant associations of type 1 diabetes with any of the MHC genes, but dramatically reduced significance with TNXA (P = 2.6 × 10−9 before adjustment; P = 2.4 × 10−4 after adjustment)." (PMID 22951892, 2012).
cancer (2 papers, 2021 to 2022). A tumor composed of atypical neoplastic, often pleomorphic cells that invade other tissues. "Regarding the whole map, TNXA induces a hub that enriches a variety of biological processes relevant to cancer." (PMID 35456196, 2022).
TNXA also shares sentences with these, for which no sentence is quoted: 21-hydroxylase deficiency (1 paper); chronic kidney disease (1); Duchenne muscular dystrophy (1); immune system disease (1); migraine (1); nephrotic syndrome (1); neurofibromatosis type II (1); Obesity (1); tuberculosis (1); tumor (1).